MATCAP1 (microtubule associated tyrosine carboxypeptidase 1)
Description:
Tyrosine carboxypeptidase that removes the C-terminal tyrosine residue of alpha-tubulin, thereby regulating microtubule dynamics and function. Also able to remove the C-terminal phenylalanine residue of alpha-tubulin TUBA8. Recognizes adjacent tubulin dimers along the same protofilament.
Synonyms: KIAA0895L; LOC653319; TMCP1
Tractability: Small molecule: a structure with a bound ligand is known.
Gene: Protein-coding gene on chromosome 16 (67,175,599 to 67,184,228, reverse strand). Ensembl gene ENSG00000196123.
Subcellular location: Cytoplasm, cytoskeleton
Subcellular location (Human Protein Atlas): Nucleoplasm; Vesicles
Gene Ontology:
Molecular function: metallocarboxypeptidase activity; protein binding; tubulin-tyrosine carboxypeptidase
Biological process: brain development
Cellular component: microtubule; cytoskeleton
Genetic constraint (gnomAD): Loss-of-function variants: 28 observed, 39.68 expected, observed/expected ratio (o/e) 0.71, 90% interval 0.52 to 0.97. The upper end of that interval is the gene's LOEUF score, 0.97, which puts it in group 4 of 6, group 1 being the genes least tolerant of losing a copy. Missense variants: 530 observed, 613.24 expected, observed/expected ratio (o/e) 0.86, 90% interval 0.8 to 0.93. Synonymous variants: 217 observed, 243.13 expected, observed/expected ratio (o/e) 0.89, 90% interval 0.8 to 1.
Homologues: Orthologues: chimpanzee MATCAP1 (99% identical), macaque MATCAP1 (99% identical), dog MATCAP1 (93% identical), pig MATCAP1 (93% identical), rabbit MATCAP1 (91% identical), guinea pig MATCAP1 (88% identical), rat Matcap1 (85% identical), mouse Matcap1 (83% identical), tropical clawed frog matcap1 (59% identical), zebrafish kiaa0895l (58% identical). Paralogues in human: MATCAP2 (48% identical).